INS (insulin)
Diseases named in the same sentence as INS in open-access papers (continued):
Sharing a sentence is not in itself a finding about the gene and the disease.
Insulin resistance (continued). "The neuron-specific IR knockout mice (NIRKO) had hyperphagia, the increased body weight, hyperglycemia, moderate insulin resistance, and the increased levels of insulin, leptin and triglycerides." (PMID 28031898, 2015). "There are many studies focusing on changes in β-cell regeneration, insulin secretion, and insulin resistance after TAC administration." (PMID 26599323, 2015). "Insulin resistance and impaired insulin secretion are considered as primary pathophysiological factors in the development of T2DM." (PMID 25924608, 2015). "An impaired insulin signaling secondary to insulin resistance promotes a maladaptive UPR with an impaired spliced XBP1 nuclear translocation and is characterized by ATF6 and CHOP signaling in diabetic nephropathy." (PMID 26545114, 2015). "Insulin resistance (IR) is a condition in which the reactivity of a target organ to blood insulin is reduced, and is known to be the strongest predictor of type 2 diabetes mellitus occurrence." (PMID 26146523, 2015). "Insulin resistance in the liver has been viewed as a central feature of the pathophysiology of metabolic disorders, including glucose intolerance, dyslipidemia, and insulin action." (PMID 25888638, 2015). "Several insulin resistance/sensitivity indices are calculated from plasma glucose and insulin in the fasting state and during OGTT." (PMID 25615826, 2015). "IFN-γ attenuates insulin sensitivity and reduced lipid storage in human adipocytes and has a role in regulating systemic inflammation and insulin resistance in obesity (O’Rourke, White, Metcalf, Winters, Diggs, Zhu, & Marks, 2012)." (PMID 26755467, 2015). "Convincing evidence showed that oxidative stress is a deleterious factor leading to insulin resistance, β-cell dysfunction, impaired glucose tolerance, and ultimately, type 2 diabetes, with elevated markers of oxidative stress in insulin-resistant subjects." (PMID 25947580, 2015). "Subjects who were born late preterm had higher fasting and 2-hour insulin concentrations and higher indices of homeostatic model assessment for insulin resistance than did the controls." (PMID 25947956, 2015). "Skeletal muscle is a primary site of insulin stimulated glucose disposal and any dysfunction in this process can lead to the development of insulin resistance (IR), preceding T2D." (PMID 26610527, 2015). "Serum insulin, the insulin resistance index and TG increased gradually, and these increases were accompanied by decreasing HDL-C and glucose tolerance." (PMID 26358367, 2015). "Blood samples were obtained for estimation of total cholesterol and triglycerides, insulin, glucose, insulin resistance, tumor necrosis factor alpha (TNF-α), interleukin 12 (IL12), and interleukin 10 (IL-10)." (PMID 25944984, 2015). "The reduction of mtDNAn was strongly associated with insulin resistance (HOMA-IR: −0.703, p < 0.05; fasting insulin level: −0.015, p < 0.05); by contrast, the correlation between fasting glucose or lipid levels and mtDNAn was not significant." (PMID 26110043, 2015). "Future research will determine if improving insulin resistance using insulin-sensitizers or lifestyle changes can improve diastolic function." (PMID 25582424, 2015). "Increases in HOMA-ir and serum insulin concentration are the representative parameter of insulin resistance." (PMID 25945322, 2015). "Both insulin deprivation and insulin resistance attenuate the activity of lipoprotein lipase, a key enzyme in the removal and degradation of triglycerides from circulation." (PMID 26003803, 2015). "During the development of T2D, western diets rich in saturated fats increase plasma lipid levels, which leads to obesity and insulin resistance, thereby aggravating compensatory insulin secretion in pancreatic β-cells." (PMID 26147439, 2015). "Since there is a relative insulin resistance, women with PCOs produce higher levels of insulin than they otherwise would have." (PMID 25866577, 2015).
Insulin resistance (continued). "In diabetic patients on oral agents with presumably mild to moderate insulin resistance, glucose control was successful with incretins alone, but insulin was required in those with significant insulin resistance." (PMID 28702223, 2015). "Data from mouse models discordant for obesity and insulin resistance (AKT2 KO, Adiponectin aP2-transgenic), suggested that scWAT TAG Elovl6 ratio was associated with insulin sensitivity, whereas SCD1 ratio was associated with fat mass." (PMID 26679101, 2015). "In our laboratory, we have studied an experimental model of protein restriction in early life that demonstrates deficits in insulin secretion and liver insulin resistance in adulthood." (PMID 25892856, 2015). "Subjects with IFG are known to have hepatic insulin resistance, but normal peripheral insulin sensitivity; while subjects with IGT are known to have normal or mild hepatic, but marked peripheral insulin resistance." (PMID 26500686, 2015). "The authors further found that hepatocyte HO-1 knockout mice were insulin hypersensitive, while overexpression of HO-1 exacerbated insulin resistance, steatosis, and metabolic dysfunction." (PMID 26693205, 2015). "T2D is a metabolic disorder characterized by chronic hyperglycemia due to insulin resistance and/or impaired insulin secretion." (PMID 25961052, 2015). "The first was to utilize a low physiological dose of insulin to determine the effects of voluntary physical activity on the prevention of insulin resistance in mice." (PMID 25713323, 2015). "T2D is characterized by insufficient secretion of insulin from the β-cells of the pancreatic islets, coupled with impaired insulin action in target tissues such as muscle, liver and fat (a condition termed insulin resistance)." (PMID 25982967, 2015). "Insulin resistance is characterized by impaired insulin signaling, which is a precursor to type 2 diabetes." (PMID 26266809, 2015). "On the basis of these reports, the adverse effects of cigarette smoking on glycemia seem to be mediated through both insulin resistance and impaired insulin secretion." (PMID 25822499, 2015). "Our data suggested that HPN suppressed insulin resistance by restoring PA-inhibited insulin signaling in HepG2 cells, including insulin-stimulated tyrosine phosphorylation of IRβ and IRS1/2 and serine phosphorylation of Akt." (PMID 26193288, 2015). "ZDF rats showed marked and significant increases (P<0.01) in plasma glucose and insulin levels as well as insulin resistance (HOMA index) in comparison with ZL rats." (PMID 26413386, 2015). "Insulin resistance is defined as a decreased ability of target tissues such as fat, liver, and skeletal muscle to respond to insulin and is a characteristic feature of type 2 diabetes." (PMID 26106625, 2015). "The experimental group showed a favorable improvement in insulin concentration and insulin resistance (p = 0.001; 0.01 respectively) compared to the placebo group." (PMID 26593941, 2015). "Body mass index (BMI), waist circumference (WC), fasting insulin and glucose serum levels, insulin resistance (assessed by using the homeostasis model assessment [HOMAIR]), and 24-h aldosterone urine levels were measured." (PMID 26419359, 2015). "In conclusion, TAK-242 and E5564 partially reversed acute lipid-induced insulin resistance in rats by lowering hepatic glucose production and restoring insulin-stimulated Rd." (PMID 26196892, 2015). "Diabetes ensues when the pancreatic β-cell cannot compensate for insulin resistance by adequately increasing insulin secretion." (PMID 25951943, 2015). "The i.p. total body insulin tolerance test is insensitive to discrete changes in hepatic insulin resistance." (PMID 26168159, 2015). "In the presence of myocardial insulin resistance 1 wk after MI, we observed blunted insulin stimulation of Akt and ERK1/2 phosphorylation with concomitant enhanced p38 MAPK phosphorylation characteristic of pathway-selective insulin resistance." (PMID 26659007, 2015).
Insulin resistance (continued). "The mice lacking osteoblasts have not only problems on bone density and strength but also impaired glucose metabolism, such as high blood glucose, low insulin secretion, and insulin resistance." (PMID 25873961, 2015). "Insulin resistance is a physiological disorder, under which the cells fail to respond to the normal actions of the hormone insulin, though it is sufficiently produced by the body – this impairment leads to hyperglycemia (i.e., type 2 diabetes)." (PMID 25972911, 2015). "Even in the thinner individuals who make up this cohort, higher weight and weight increase (and specifically fat-mass) predicted higher risk for increased insulin resistance, while untreated HIV disease was associated with increasing insulin sensitivity." (PMID 25880634, 2015). "During pathophysiology of type 2 diabetes, as insulin resistance developed, β-cells compensatorily secret more insulin." (PMID 25741510, 2015). "Administration of vaspin to obese mice improves glucose tolerance and insulin sensitivity and modifies the expression of genes involved in insulin resistance." (PMID 25918733, 2015). "The IRAS study demonstrated that HR was prospectively predictive of both insulin resistance and decreased insulin secretion." (PMID 25973404, 2015). "Management of CKD with dialysis reduces insulin resistance and increases insulin degradation and this includes an improvement in hepatic insulin metabolism." (PMID 26239457, 2015). "It is characterized by an impaired compensatory increase in insulin secretion to overcome the pregnancy-induced insulin resistance." (PMID 25973943, 2015). "The homeostasis assessment model of insulin resistance (HOMA-IR) was calculated using the formula: [fasting insulin (pmol/l) × fasting glucose (mmol/l)]/135." (PMID 25793007, 2015). "Insulin resistance reduces glucose tolerance especially in adipocytes and muscle cells, in which glucose uptake is insulin." (PMID 26640706, 2015). "Blood glucose and insulin were higher, and glucose intolerance, insulin intolerance, and insulin resistance were increased in arsenic-treated ovariectomized mice compared with arsenic-treated sham mice." (PMID 25859628, 2015). "Serum insulin and blood glucose were analyzed to estimate insulin resistance, a known complication of obesity." (PMID 26539241, 2015). "Increased Ang II stimulation of NADPH oxidase-derived ROS activates NFκB inflammatory pathway, which in turn impairs insulin signaling and Glut-4 translocation in the skeletal muscle and induces systemic insulin resistance." (PMID 25928697, 2015). "Insulin resistance is improved by NO at various levels including insulin secretion, mitochondrial function, modulation of inflammation, insulin signaling and glucose uptake." (PMID 26091235, 2015). "We used a 75-g oral glucose tolerance test (OGTT) and fasting blood glucose and insulin concentrations to diagnose type 2 diabetes and assess insulin resistance and sensitivity." (PMID 26277879, 2015). "Insulin resistance (IR) is defined as decreased sensitivity or responsiveness to the metabolic actions of insulin, such as insulin-mediated glucose disposal and inhibition of hepatic glucose production." (PMID 27525252, 2015). "Epidemiologic studies suggest that low vitamin D levels are related to impaired glucose clearance, insulin secretion, and insulin resistance." (PMID 26061015, 2015). "In obese horses insulin resistance reduces the ability of insulin to inhibit hormone-sensitive lipase, resulting in elevated plasma NEFA concentrations." (PMID 25938677, 2015). "Hepatic insulin resistance in men with high IHTG was characterized by impaired efficacy of insulin in suppressing all three sources of glucose production rather than reduced efficacy in suppressing a particular pathway." (PMID 25250633, 2015). "Elevated plasma FFAs promote peripheral and hepatic insulin resistance, reduce basal and insulin-stimulated glucose uptake in muscle by inhibiting insulin signaling." (PMID 26580649, 2015).
Insulin resistance (continued). "The homoeostasis model assessment of insulin resistance (HOMA-IR) is an established measure of whole-body insulin sensitivity, the higher the value the more insulin resistant." (PMID 26383020, 2015). "We assessed correlations between physical activity level and waist circumference, blood pressure, fasting levels of plasma glucose, serum triglycerides, and insulin and homeostasis model assessment-insulin resistance (HOMA-IR)." (PMID 26064983, 2015). "Since insulin resistance plays a critical role in liver carcinogenesis, the effects of metformin treatment on serum levels of glucose and insulin and on improvements in insulin resistance were examined." (PMID 25879666, 2015). "Previous works using different animal models of insulin resistance showed that RSV was able to improve insulin secretion, although the exact mechanism of its action is still poorly elucidated." (PMID 25774684, 2015). "21-week-old GK rats exhibited complete insulin resistance in both adipose tissue and skeletal muscle while Wistar rats retained normal insulin sensitivity." (PMID 26236746, 2015). "The T2DM stage is characterized by substantial decompensation produced by insufficient insulin secretion in the face of either central or peripheral insulin resistance." (PMID 26555895, 2015). "25( OH )D is believed to have some roles in insulin release, expression of insulin receptors, and suppression of cytokines that are possible mediators for insulin resistance." (PMID 25918586, 2015). "We assume that insulin glycation not only can explain insulin resistance, but also can play a role in cell death through lipid peroxidation more importantly glial cells." (PMID 26311627, 2015). "Further, the HF3 fetuses were also insulin resistant evident by their higher HOMA-insulin resistance values compared to the control fetuses." (PMID 26343716, 2015). "Both a deterioration of insulin secretion and an aggravation of insulin resistance are two pivotal defects in the pathogenesis of DM." (PMID 26471283, 2015). "The effect of insulin resistance can be exacerbated by impairment of the role of insulin in maintaining the hepatic glucose balance." (PMID 25750607, 2015). "A strong negative correlation between lipin 1 mRNA levels in adipose tissue and glucose levels, insulin levels, and insulin resistance has been described in mice and humans." (PMID 26086818, 2015). "This study shows that insulin is a potent stimulator of GU in the healthy intestine and that intestinal insulin resistance is ameliorated after bariatric surgery." (PMID 25631620, 2015). "Insulin resistance refers to a condition where cells in the body become resistant to the effects of insulin, which means the normal response to a given amount of insulin is reduced." (PMID 25569521, 2015). "This feed-forward model explains why the osteoblastic InsR knocked out mice have low serum insulin level and high insulin resistance." (PMID 25873961, 2015). "Here, we showed that in vitro administration of microbe-derived EVs induced insulin resistance including impairment of insulin signaling and decrease in GLUT4 translocation in myotubes." (PMID 26510393, 2015). "Oral hypoglycemic agents (OHAs) such as sulphonylureas (SUs) and glinides promote insulin secretion and insulin therapy complement insulin secretion, while biguanide and thiazolidine improve insulin resistance." (PMID 25699116, 2015). "Due to reduced β cell function and lower insulin resistance, insulin secretagogues such as sulfonylureas (SU) and glinides or insulin injections have been used in the management of T2DM in Japan." (PMID 25944304, 2015). "Given insulin resistance is defined as a condition in which insulin signals fail to work, despite the presence of a sufficient amount of insulin., reduced cellular responsiveness to IGF is put into IGF resistance." (PMID 26637371, 2015).
Insulin resistance (continued). "The areas under the receiver operating characteristics curves for metabolic syndrome were 0.670 (across HbA1c values) and 0.770 (across insulin values), and, for insulin resistance, 0.647 (HbA1c) and 0.995 (insulin)." (PMID 26241903, 2015). "It has been shown that anthocyanins increase insulin secretion from pancreatic β-cells and improve insulin resistance." (PMID 26508984, 2015). "In a study undertaken in Iran, daily consumption of probiotic yogurt for 9 weeks maintained serum insulin levels, potentially preventing pregnant women from developing insulin resistance." (PMID 25580813, 2015). "The IGF system and insulin signaling pathway simultaneously play important roles in hyperinsulinemia, insulin resistance and tumor pathogenesis, which are more likely to be the potential mechanisms in a variety of human cancers." (PMID 26222906, 2015). "Elevated insulin levels are known to reduce biological responses, leading to insulin resistance and subsequently glucose intolerance, endothelial dysfunction, elevated inflammatory markers, cardiovascular disease, hypertension, and certain forms of cancer." (PMID 25695047, 2015). "IRS-1 serine phosphorylation (IRS-1pSer) blocks the downstream insulin signaling, which triggers, in turn, peripheral insulin resistance." (PMID 26136647, 2015). "Flavonoids can improve insulin resistance via a decreasein adipose tissue and hepatic inflammation, hepatic oxidative stress attenuation and increase in insulin mediated processes in liver, muscle, and adipose tissue." (PMID 26157708, 2015). "One-time blood draw for fasting glucose and insulin were used to calculate insulin resistance using homeostasis model assessment for insulin resistance (HOMAIR)." (PMID 27747313, 2015). "As shown in previous studies, curcumin has a beneficial role in improving insulin resistance and lowering blood glucose in db/db mice through the elevation of plasma insulin levels, which enhances the activation of glycolysis and inhibits gluconeogenesis." (PMID 26839808, 2015). "Metformin also markedly decreased serum levels of insulin and reduced insulin resistance, and inhibited phosphorylation of Akt, mammalian target of rapamycin (mTOR), and p70S6 in the liver." (PMID 25879666, 2015). "Acute administration of [L28K]esculentin-2CHa (75 nmol/kg body weight) to high fat fed mice with obesity and insulin resistance enhanced glucose tolerance and insulin secretion." (PMID 26512980, 2015). "Elevated NEFA concentrations exacerbate insulin resistance by diminishing insulin-stimulated glucose intake in muscles, directly affecting insulin signaling, activating gluconeogenesis and triglyceride synthesis in liver, and contributing to β-cells failure." (PMID 25838947, 2015). "Fasting insulin levels, value of homeostasis model assessment of insulin resistance (HOMA-IR), and serum high sensitive C-reactive protein (hs-CRP) levels were evaluated." (PMID 26599361, 2015). "Insulin resistance, defined as a state of reduced insulin secretion or inability of insulin to optimally stimulate transport of glucose into the peripheral tissues, is a major player in the pathogenesis of the metabolic syndrome and type 2 diabetes." (PMID 27446819, 2015). "Second, we did not have biochemical data such as hormonal profiles, blood glucose levels, hemoglobin A1C concentrations, insulin, C-peptide levels, or calculation of homeostasis model assessment for insulin resistance for evaluating their impact." (PMID 26171401, 2015). "Type 2 diabetes, a heterogeneous disorder characterized by impaired insulin secretion and insulin resistance, is closely related to obesity." (PMID 25924608, 2015). "Twice daily intraperitoneal (i.p.)injections of Aβ1-42 in 10-week old, male C57BL/6J mice (on standard lab chow) induced hepatic insulin resistance, reduced hepatic insulin signaling, and increased fasting blood sugar levels." (PMID 26340637, 2015).